TYK2 (tyrosine kinase 2)
Diseases named in the same sentence as TYK2 in open-access papers (continued):
Sharing a sentence is not in itself a finding about the gene and the disease.
COVID-19 (75 papers, 2020 to 2025). A disease caused by infection with severe acute respiratory syndrome coronavirus 2. "Genome-wide association studies (GWAS), including data from the COVID-19 Host Genetics Initiative, have demonstrated that loss-of-function mutations in TYK2 are protective against severity disease." (PMID 40410684, 2025). "Evidence to date shows controversy about the role of TYK2 in COVID-19 severity, reporting association with its overexpression or its deficiency." (PMID 41445728, 2025). "In summary, the identification of TYK2 gene variants as predictors of COVID-19 severity has important implications for risk stratification and the development of targeted therapeutic interventions." (PMID 40543387, 2025). "This duality underscores the complex role of TYK2 in immune regulation and highlights the importance of considering variant-specific effects when evaluating the gene’s impact on COVID-19 outcomes." (PMID 40543387, 2025). "To offer potential therapeutic strategies and contribute to better patient care and treatment decisions, we would like to summarize the current findings on the association of IFNAR2 and TYK2 genes with COVID-19 pathology and propose future challenges." (PMID 39351231, 2024). "The type I interferon response is one of three major pathways that affect susceptibility to and severity of COVID-19, and TYK2 (located at 19p13.2) contains candidate pathogenic genes associated with the type I interferon pathway." (PMID 38699234, 2024). "Specifically, ten phenotypes were associated with a genetic variant called rs74956615 (TYK2), all showing reduced odds related to the COVID-19 risk allele." (PMID 39351231, 2024). "A higher expression of IFNAR2 was linked to a reduced probability of critical COVID-19, and TYK2 expression had a role in regulating IFNAR signaling." (PMID 38741892, 2024). "The study showed that low IFNAR2 expression and high TYK2 expression levels are linked to COVID-19 severity." (PMID 39435115, 2024). "AR IFNAR1, IFNAR2, TBK1, and STAT2 deficiencies were subsequently reported in children with critical COVID-19, and AR TYK2 deficiency was identified in children with COVID-19 pneumonia." (PMID 37196358, 2023). "Rs2277732 (DPP9), rs13081151 (FLT1P1), and rs11085727 (TYK2), among others, were considered significantly associated3with OA-COVID-19 hospitalization combined trait." (PMID 37398645, 2023). "In July 2021, the COVID-19hg conducted an international meta-GWAS to increase the number of COVID-19 patients to 49,562, and newly reported the association of SLC6A20 with COVID-19 susceptibility and TYK2 with COVID-19 severity." (PMID 35264675, 2022). "TYK2 variant rs74956615 has been correlated with severity of COVID-19, where high TYK2 expression is associated with critically ill and hospitalized patients." (PMID 36072602, 2022). "CCR2 (encoding CC chemokine receptor type 2) and TYK2 (encoding tyrosine kinase 2) were identified as genetic mediators of COVID-19 critical illness in an unbiased search of genetic mechanisms behind this phenotype to identify causal variants." (PMID 36009555, 2022). "A higher gene expression of Tyk2 is also associated with severe COVID-19 in a genome-wide association study." (PMID 35563697, 2022). "The COVID-19 risk allele (T), that correlates with increased TYK2 transcript expression, correlated with reduced amounts of SERPING1 and CXCL10 proteins in plasma (p = 0.0003)." (PMID 36327221, 2022). "The severe COVID-19 risk allele promotes inclusion of exon 8 in TYK2 that is essential for TYK2 binding to cognate receptors." (PMID 36327221, 2022). "Our study shows that the rs1799752/ACE1, rs1990760/IFIH1, rs2236757/IFNAR2, rs12329760/TMRPSS2, and rs2304256/TYK2 polymorphisms are genetic risk factors for severe forms of COVID-19 and increased mortality." (PMID 36672770, 2022). "Signal-A at TYK2 is likely driven by a coding P1104A variant (rs34536443) whose COVID-19 risk allele has been shown to impair TYK2 target phosphorylation." (PMID 36327221, 2022).
COVID-19 (continued). "While DPP9 and TYK2 are thought to be associated with host-driven inflammatory lung injury linked to life-threatening COVID-19, IFNAR2 and OAS genes have been associated with innate antiviral defences." (PMID 34575070, 2021). "Autosomal-recessive and autosomal-dominant mutations in interferon pathway genes have been identified in some patients with life-threatening COVID-1932 and high TYK2 expression was linked to COVID-19 disease severity." (PMID 34079039, 2021). "In a recent study it was found a causal link between life-threatening COVID-19 and high expression of TYK2, the gene encoding Tyrosine Kinase 2, a member of the JAK family kinases." (PMID 33467029, 2021). "Of great interest, during the peer review process of this perspective, the GenOMICC study identified TYK2 association with critical illness in COVID-19." (PMID 33414783, 2020). "Their findings suggest that TYK2 single nucleotide polymorphisms may serve as genetic markers for identifying individuals at increased risk of severe COVID-19." (PMID 40543387, 2025). "The TYK2 gene, previously discussed for its association with increased COVID-19 severity, also harbors polymorphisms that may confer a protective effect." (PMID 40543387, 2025). "Recent studies have identified specific variants of Tyk2 associated with COVID-19 outcomes." (PMID 40410684, 2025). "The TYK2 locus shows a significant genetic association with severe COVID-19." (PMID 38699234, 2024). "We extended the analysis to two other type I IFN-related genes, TLR7 and TYK2, that we had recently found to be associated with critical COVID-19, and to branchpoint (BP) variants with a potentially strong impact on the splicing of the 15 type I IFN-related genes." (PMID 37020259, 2023). "Recently, a TYK2 missense mutation has been reported to confer high risk for COVID-19 severity." (PMID 35602518, 2022). "Other genes commonly implicated in coronavirus disease 2019 include ACE2, IL6, DPP9, TYK2, TMPRSS2, FOXP4, and TNF, while the emerging genes consist of FURIN, CXCL10, OAS1, OAS2, OAS3, and ISG15." (PMID 35454970, 2022). "Using WES data, we focused on nine genes that have been reported to be involved in the SARS-CoV-2 entry pathway (ACE2, RAB7B, ADAM17, TMPRSS2), host immune response (IFNAR2, TYK2), and/or were previously shown to be associated with COVID-19 outcomes (DPP9, LZTFL1, SLC6A20)." (PMID 36292769, 2022). "We confirmed the existence of the 3p21.31 region (LZTFL1, SLC6A20) implicated in the susceptibility to SARS-CoV-2 infection and TYK2 gene might be involved in COVID-19 severity." (PMID 34945790, 2021). "Indeed, the converse association observed in the TYK2 variant with severe COVID-19 may indicate that the reduced immune response due to a higher ratio of TYK2_1 may result in insufficient responses to the coronavirus." (PMID 39288763, 2024). "Therefore signal-B comprises evidence for two functional effects with respect to COVID-19 risk alleles, one of which increases function of TYK2 through altered splicing (rs2304256 (V362F)) and one that is correlated with increased expression of TYK2 (rs11085727)." (PMID 36327221, 2022). "Similarly, these TYK2 variants may be associated with disease manifestation, as well as the response to Jak inhibitors (Jakinibs) in COVID-19." (PMID 33414783, 2020). "Functionally, relevant mutations and polymorphisms in JAK family proteins, including TYK2, JAK1, JAK2, and JAK3, have been associated with diverse immune-related diseases and have now been implicated in COVID-19 severity and susceptibility." (PMID 40410684, 2025). "A study demonstrated that the expression of the TYK2 gene was reduced in COVID-19 patients compared to healthy individuals." (PMID 38741892, 2024). "In COVID-19, expression of interferon α/β receptor subunit (IFNAR) 2 and tyrosine kinase 2 (TYK2) has been suggested to be associated with COVID-19 outcomes." (PMID 39351231, 2024).
COVID-19 (continued). "Our study revealed that IFNAR2 and TYK2 mRNA expressions were significantly downregulated in COVID-19 patients compared to healthy subjects." (PMID 39351231, 2024). "Four upregulated common genes (DHX15, USP14, COPS3, TYK2) and one downregulated common feature gene (RIOK2) were identified and showed good diagnostic accuracy for T2DM and COVID-19." (PMID 38699234, 2024). "Furthermore, TYK2 SNPs may be used to determine high-risk individuals for severe COVID-19." (PMID 38741892, 2024). "Despite discrepancies in findings regarding the downregulation of IFNAR2 and TYK2 in COVID-19 patients, the importance of these genes in the pathogenesis of COVID-19 remains prominent." (PMID 38741892, 2024). "Several genetic loci, such as the TYK2 and DPP9 genes, have been identified that affect COVID-19 susceptibility and severity." (PMID 39170247, 2024). "Specifically, we observed a negative correlation between the expression levels of IFNAR2 and TYK2 transcripts in COVID-19 patients." (PMID 39351231, 2024). "According to recent research, severe instances of COVID-19 were associated with decreased expression of IFNAR2 at 21q22.1 and increased expression of a gene near TYK2 at 19p13.2." (PMID 38741892, 2024). "There was a negative correlation between the expression levels of IFNAR2 and TYK2 transcripts in COVID-19 patients (p-value = 0.044; partial correlation coefficient = -0.283)." (PMID 38741892, 2024). "Nevertheless, the potential of IFNAR2 and TYK2 expressions as prognostic biomarkers for COVID-19 has yet to be fully established." (PMID 38741892, 2024). "We were unable to comment definitively on the prognostic power of IFNAR2 and TYK2 expressions in COVID-19 patients, and larger-scale studies are needed." (PMID 38741892, 2024). "Additionally, rs12720270 may downregulate coronavirus disease 2019 severity by decreasing TYK2 expression." (PMID 39726748, 2024). "Our findings also demonstrate a significant reduction in the expression levels of IFNAR2 and TYK2 among COVID-19 patients." (PMID 38741892, 2024). "In an extended sample of 3269 patients with critical COVID-19, we identified 57 patients carrying a rare predicted LOF variant at 14 type I IFN-related influenza susceptibility loci (including TYK2) or with biochemically proven TLR7 deficiency." (PMID 37196358, 2023). "In the COVID-19 group, the TYK2 rs2304256, OAS1 rs10774671, CD40 rs4813003 and FCGR2A rs1801274 homozygote and heterozygote frequencies were in accordance with those indicated by the Hardy–Weinberg principle (p > 0.05)." (PMID 37896870, 2023). "TYK2 and IL10RB are in Type III interferon signaling, and IL10RB is the top key regulator of COVID-19 host susceptibility." (PMID 37886583, 2023). "Among these, 16 pleiotropic genes were targets of drugs, such as tofacitinib and baricitinib targeting TYK2 for the treatment of ulcer colitis and COVID-19, respectively." (PMID 38102678, 2023). "Tofacitinib, an inhibitor of TYK2, has been used in the treatment of ulcerative colitis, and baricitinib has been approved for the treatment of COVID-19." (PMID 38102678, 2023). "In COVID-19 patients, a significant decrease in TYK2 level was observed in male patients compared to male controls." (PMID 37704909, 2023). "A GWAS study using genetic data from 2244 critically ill COVID-19 patients from UK ICUs has recently identified IFNAR2 and TYK2 as candidate genes significantly associated with severe COVID-19." (PMID 36292769, 2022). "Our qRT-PCR results demonstrated that CBD and THC significantly reduced the elevated expression of Tyk2, a JAK implicated in the severity of COVID-19, post-LPS treatment in THP-1 macrophages and HBECs." (PMID 35563697, 2022). "Genome-wide association studies (GWAS) have described polymorphisms in other COVID-19 candidate genes, such as DPP9 and TYK2, which have increased prevalence in COVID-19 patients." (PMID 36672770, 2022).
COVID-19 (continued). "JAK is a family of tyrosine kinases, and an increased expression of its member, tyrosine kinase-2 (TYK2), has been recently implicated in life-threatening COVID-19 in a genome-wide analysis of 2636 patients." (PMID 35563697, 2022). "Five essential genes (IFNAR2, TYK2, OAS1, DPP9, and CCR2) have been linked to the most severe forms of COVID-19 disease, suggesting possible drug targets and vaccine epitopes." (PMID 35454970, 2022). "mRNA levels of ADAM17, IFITM3, IL6, CXCL10, CXCL11, IFNG and TYK2 were increased in PBCs of COVID-19 patients (n = 73) compared with controls (n = 47), independently of sex." (PMID 36009555, 2022). "In this work, we detected the clinical significance of IFNAR2 (2 SNPs), SLC6A20 (1 SNP) with respect to COVID-19 susceptibility and ADAM17 (2 SNPs), TMPRSS2 (1 SNP), TYK2 (1 SNP), DPP9 (1 SNP) with respect to the severity of the disease." (PMID 36292769, 2022). "Additional studies have also highlighted the relevance of TYK2 in COVID-19 and its involvement in COVID-19 severity." (PMID 36009555, 2022). "The COVID-19 Host Genetics Initiative (HG1) report concurred with the association of variants in ABO, SLC6A20, TYK2, DPP9, IFNAR2, and additionally reported a variant in Protein Phosphatase 1 Regulatory Subunit 15A (PPP1R15A) in influencing COVID-19 severity." (PMID 36143338, 2022). "Other innate immune genes upstream of OAS1 that are associated with severe COVID-19 in a genome wide association study are IFNAR2, and TYK2, which are in the type I IFN pathway." (PMID 34342578, 2021). "An association study based on ~50,000 COVID-19 patients further supported the association of genetic variants in ABO, TYK2, DPP9, IFNAR2, SLC6A20 and Protein Phosphatase 1 Regulatory Subunit 15A (PPP1R15A) with the severity of COVID-19." (PMID 34575070, 2021). "The expression of genes IFNAR2 and TYK2 was found to be related to critical illness and severity of COVID-19 symptoms." (PMID 34411000, 2021). "Several JAK inhibitors, e.g., ruxolitinib (JAK1/2), baricitinib (JAK1/2), and tofacitinib (JAK1/2/3, TYK2), are currently in clinical trials for COVID-19." (PMID 34439323, 2021). "This study showed that interferon α and β receptor subunit 2 gene (IFNAR2), tyrosine kinase 2 gene (TYK2) and chemokine receptor type 2 gene (CCR2) gene were associated with severity of COVID-19." (PMID 33396837, 2020). "Additionally, IFNAR2 and TYK2 were significantly downregulated in the COVID-19 group compared to healthy subjects (p-value = 0.002 and p-value = 0.028, respectively)." (PMID 38741892, 2024). "After adjusting for potential confounding factors (age, sex, and history of COVID-19 vaccination injection), we observed a negative correlation between the expression levels of IFNAR2 and TYK2 transcripts in COVID-19 patients (p-value = 0.044; partial correlation coefficient = -0.283)." (PMID 38741892, 2024). "TYK2 plays a crucial role in the progression of both diabetes and COVID-19." (PMID 38699234, 2024). "The ΔCt and ΔΔCt levels for TYK2 were notably higher in the COVID-19 patients than in the controls [9.02 vs. 7.79, p-value = 0.028; 1.23 vs. 2.8571 × 10−10, p-value = 0.028, respectively,], suggesting decreased gene expression in the COVID-19 patients." (PMID 38741892, 2024). "Hence, additional research on IFNAR2 and TYK2 expression in COVID-19 can significantly contribute to finding a conclusive treatment for this worldwide crisis." (PMID 39351231, 2024). "In contrast, the anti-inflammatory therapy baricitinib, which has activity against JAK1/2 and moderate activity against TYK2, reduced mortality amongst hospitalized patients with COVID-19 by about 20%, and it has received U.S. Food and Drug Administration (FDA) approval for this indication." (PMID 38665231, 2024). "The consequences of the TYK2 gene’s (rs2304256) influence on COVID-19 are still controversial." (PMID 37896870, 2023).
COVID-19 (continued). "Finally, TYK2 mRNA levels were increased (by 107%) in COVID-19 patients compared to control subjects (Student’s t test), and the increase was evidenced in all COVID-19 severity and BMI categories (one-way ANOVA, post-hoc analysis)." (PMID 36009555, 2022). "The severe COVID-19 risk allele for signal-B at TYK2 is associated with reduced SERPING1 and CXCL10 protein expression, implying that the minor allele at signal-B in the TYK2 locus reduces some aspect of TYK2 function." (PMID 36327221, 2022). "In conclusion, this study shows an association of rs1799752/ACE1, rs1990760/IFIH1, rs2236757/IFNAR2, rs12329760/TMPRSS2, and rs2304256/TYK2 polymorphisms with worse COVID-19 outcomes, especially among female and non-white patients." (PMID 36672770, 2022). "The TYK2 locus has previously been found to be associated with SLE and severe COVID-19." (PMID 36327221, 2022). "Our results suggest that COVID-19 is causing upregulation of IgG production leading to activation of classical complement through C1S, which produces a downregulation of RUNX1 and TYK2 signaling, that blocks T-cell maturation and mutes Th1/Th17 immune response, respectively." (PMID 34899680, 2021). "A large GWAS analysis reported TYK2 as a genetic locus (rs74956615) associated with severity of COVID-19 disease caused by the novel SARS-CoV-2 virus, with high TYK2 gene expression found in critically ill COVID-19 patients." (PMID 34439323, 2021). "Thus, TYK2 is a potential target for treatment of patients with COVID-19 or viral pneumonia to combat overactive cytokine inflammation." (PMID 34439323, 2021). "Briefly, TYK2 encodes for tyrosine kinase 2 (TYK2) a protein partially targeted by Janus kinase (JAK) inhibitors like baricitinib, that have been approved for rheumatoid arthritis and successfully repurposed for severe COVID-19, although predating possible evidence from genetic studies." (PMID 38977844, 2024). "Moreover, the cohort analysis of 694 Brazilian COVID-19 patients reveals a significant link between rs2236757/IFNAR2 and rs2304256/TYK2 polymorphisms and worsened COVID-19 outcomes, particularly affecting female and non-white patients." (PMID 39351231, 2024). "Interestingly, the presence of some alleles (T in rs2304255, A in rs12720354, and G in rs12720207) of TYK2 decreases its expression and may predict COVID-19 severity." (PMID 38741892, 2024). "Furthermore, JAK3, JAK2 and TYK2, which are highly activated in COVID-19, may be co-targeted with cytokine-modulatory therapy." (PMID 38389037, 2024). "Consequently, androgen suppression of TYK2 signaling in T lymphocytes may be an important determinant of COVID-19 outcome." (PMID 35602518, 2022). "To assess the contribution of TLR7, TYK2 and OAS1 expression to COVID-19 progression over time, we conducted a longitudinal study on the expression of these three genes in patients with COVID-19." (PMID 41445728, 2025). "A significant finding emerged when comparing COVID-19 patients with controls, which demonstrated lower gene expressions of IFNAR2 and TYK2 in COVID-19 cases." (PMID 38741892, 2024). "We constructed a PPI network and identified five common feature genes (DHX15, USP14, COPS3, TYK2, and RIOK) of T2DM and COVID-19 by extracting the core genes of the network." (PMID 38699234, 2024). "We identified five common feature genes between T2DM and COVID-19: DHX15, USP14, COPS3, TYK2, and RIOK2 (where DHX15, USP14, COPS3, and TYK2 were upregulated and RIOK2 was downregulated)." (PMID 38699234, 2024). "The differentiation of CD4+ T cells, activated by the interaction of IL-23 with TYK2/Jak2, occurs with the participation of IL-6, IL-1β and TGF-β, which is extremely important in the context of the cytokine storm in COVID-19." (PMID 37896870, 2023). "Mendelian randomization and transcriptome-wide association (TWAS) assays revealed a causal link between low expression of IFNAR2, high expression of TYK2 or the monocyte/macrophage chemotactic receptor CCR2 and life-threatening COVID-19." (PMID 34571706, 2021).